PCBP1 (poly(rC) binding protein 1)
Diseases named in the same sentence as PCBP1 in open-access papers (continued):
Sharing a sentence is not in itself a finding about the gene and the disease.
tumor (continued). "PCBP1 has been proposed to suppress tumors by binding mRNA and stabilizing tumor suppressor mRNAs, repressing translation of oncogenic mRNAs, and inhibiting oncogenic splicing." (PMID 33692367, 2021). "PCBP1 regulates the alternative splicing, translation and RNA stability of many cancer-related genes and has been identified as a potential tumour suppressor gene." (PMID 34857818, 2021). "Accumulating evidence show that Poly C Binding Protein 1 (PCBP1) is deleted in distinct types of tumors as a novel tumor suppressor, but its tumor suppression mechanism remains elusive." (PMID 32922440, 2020). "Together, our results clearly demonstrated that PCBP1 coordinately inhibits intrinsic tumor cell autophagy and favors cell apoptosis for tumorigenesis inhibition." (PMID 32922440, 2020). "Recently, PCBP1 as a novel tumor suppressor is characterized to be downregulated in many cancer types on inhibition of tumor formation and metastasis, including gastric cancer and thyroid cancer." (PMID 32922440, 2020). "We recently showed that PCBP1 also increases cell cycle inhibitor, p27Kip1 expression via its RNA binding capability to repress tumor cell cycle progression." (PMID 32922440, 2020). "PCBP1 as one of the the RBPs inhibited the tumor formation and metastasis by translation silencing, mRNA alternative splicing, or transcription of carcinogenic genes." (PMID 32552766, 2020). "In line with this, our results thus have shown that for the tumor progression, in some circumstances, PCBP1 expression is inevitably repressed to induce relatively high autophagic level." (PMID 32922440, 2020). "Given that autophagy plays different roles in tumorigenic outcome, to examine tumor cell fate upon autophagy retardation by PCBP1 in the normal culture conditions, we analyzed the apoptotic status of cells with PCBP1 aberrant overexpression." (PMID 32922440, 2020). "Most of these genes, including SREBF1, CALM1, PCBP1, COTL1 and BTK, are tumor-related genes, which have been reported to be associated with tumorigenesis, progression and therapy." (PMID 32832275, 2020). "In summary, combining our current and previous results, we conclude that PCBP1 plays a coordinate role in inhibiting tumorigenesis via blocking autophagy, and in turn promoting tumor cell apoptosis." (PMID 32922440, 2020). "p27 mRNA level is correlated to PCBP1 level in the paired normal (N) and tumor (T) samples of colon tissues." (PMID 30086790, 2018). "To further assess if PCBP1 has non-p27 effect on tumor formation, we individually silenced PCBP1 and p27 expression in DLD-1 cells and conducted the tumor formation in vivo." (PMID 30086790, 2018). "We analyzed PCBP1 and p27 expression in ovary, colon and renal tumor samples and adjacent non-tumor tissues using RT-PCR, Western Blotting and immunohistochemistry." (PMID 30086790, 2018). "But based on our results, additionally silencing p27 in PCBP1-overexpressing cells can almost neutralized PCBP1’s effect, indicates the dominant PCBP1-p27 signaling in tumor suppression." (PMID 30086790, 2018). "Our results here may unveil the puzzle that loss of PCBP1 destabilizes p27 mRNA at the first step to lead to low p27 expression, irrespective of Skp2 levels and the posttranslational regulation via other manners, since Skp2 expression is rarely seen to be upregulated in the detected tumor samples." (PMID 30086790, 2018). "Our results showed that although silence of PCBP1 clearly promoted tumor formation, while p27 knockdown resulted in more aggressive tumorigenesis than PCBP1 knockdown in DLD-1 cells, indicating the multiple regulation and the key role of p27 in tumorigenesis." (PMID 30086790, 2018). "(D) Immunoblot of PCBP1 and p27 proteins in healthy tissues (N), tumor adjacent region (A) and tumor tissues (T)." (PMID 30086790, 2018).
tumor (continued). "Immunohistochemical staining of PCBP1 in representative tissue specimens obtained from metastatic tissue or tumor adjacent normal tissue exhibited robust PCBP1 staining in the control peritoneal tissues, which was significantly attenuated in the tumor tissues." (PMID 29138420, 2017). "Interactome analysis highlighted 14-3-3 zeta/delta, 14-3-3 beta/alpha, Alpha-actinin 4, HSP60, and PCBP1 as critical proteins in the tumor proteome signature based on their relative overconnectivity." (PMID 25265318, 2014). "Only five proteins were found to be significantly over-connected in the tumor proteome signature namely, PCBP1, 14-3-3 zeta, 14-3-3 beta, alpha actinin-4, and HSP60 (CH60/HSPD-1)." (PMID 25265318, 2014). "Under starvation conditions, PCBP1 promoted apoptosis of tumor cells through the autophagy pathway." (PMID 38218813, 2024). "Furthermore, SIVA-1 overexpression with DDP treatment synergistically inhibited tumor growth in vivo by increasing PCBP1 and decreasing Bcl-2 and Bcl-xL expression." (PMID 38947376, 2024). "But both SH3BGRL and PCBP1 function as tumor suppressors with their overexpression, which challenges which type of autophagy is triggered or inhibited for tumor suppression or tumor promotion, and what is the biomarker to judge the eventual function of the dual autophagy effect in tumorigenesis?" (PMID 37138798, 2023). "Another family member, PCBP1, also acts as a tumor suppressor in AML." (PMID 36452487, 2022). "However, according to current reports, the role of PCBP1 and PCBP2 in tumor is completely opposite, PCBP1 can be considered as a tumor suppressor, and PCBP2 plays a carcinogenic role." (PMID 35907982, 2022). "PCBP1 is an RNA-binding protein that was aberrantly expressed in a variety of tumor tissues." (PMID 35287546, 2022). "We demonstrate that PCBP1 is downregulated in LUAD tumour tissues." (PMID 35907982, 2022). "Furthermore, IHC analysis indicated that Ki67-positive cells in tumor tissues were significantly increased after transfected with shPCBP1 and decreased after transfected with PCBP1." (PMID 35907982, 2022). "Interestingly, PCBP1 also affected the AS of genes enriched in small molecule metabolic processes, which play an important role in tumour expansion and recurrence." (PMID 34857818, 2021). "Likewise, our results here explain the reason why PCBP1 downregulation or depletion would be an important strategy to tumor cell survival by downregulations of p62 and caspase-8." (PMID 32922440, 2020). "Since PCBP1 is recognized as a tumor suppressor in previous studies, we hypothesized that function of PCBP1 could be inhibited when bind to circ0003998, which thereby promote EMT of HCC." (PMID 32552766, 2020). "In addition, PCBP1 not only functions via autophagy, but other manners to interfere with tumor progression, for example, tumor cell cycle modulation, as tumor cell cycle can be modulated by particular autophagy during cancer development and by therapy." (PMID 32922440, 2020). "Apoptosis analysis also showed overexpression of PCBP1 could even favor tumor cell apoptosis in normal culture condition." (PMID 32922440, 2020). "So far, it remains elusive whether PCBP1 modulates and participates in tumor cell autophagy in the nutrition-efficient condition." (PMID 32922440, 2020). "Moreover, forced depletion of p27 counteracts the tumor suppressive ability of PCBP1 in the same PCBP1 over-expressing cells." (PMID 30086790, 2018). "Moreover, additional depletion of p27 in DLD-1 cells with PCBP1 overexpression disrupted the tumor-suppressive effect of PCBP1, leading to significantly accelerated tumor formation." (PMID 30086790, 2018). "Semiquantitative RT-PCR detection of PCBP1, p27 mRNA expression in conlon tumor tissues." (PMID 30086790, 2018).
tumor (continued). "Given that PCBP1 mainly regulates p27 expression at mRNA level, we compared the paired normal and tumor tissues of colon samples and found that p27 mRNA level was indeed decreased in the PCBP1 low expression tumors, validating our results from tumor cells." (PMID 30086790, 2018). "In addition, our analysis of clinical samples showed that PCBP1 was overexpressed in tumor samples from L-OHP resistant patients." (PMID 28076324, 2017). "The RNA binding protein, PCBP1 is well characterized for its role as a tumor suppressor." (PMID 29138420, 2017). "Additionally, by comparison of PCBP1 expression in tumor samples from L-OHP responsive and refractory patients, we found that PCBP1 expression was significantly higher in tumor samples from L-OHP resistant patients." (PMID 28076324, 2017). "In addition, PCBP1 expression was significantly higher in tumor samples from L-OHP refractory patients than in those from L-OHP responsive patients." (PMID 28076324, 2017). "Our findings in the current study cumulatively indicate that the RNA binding protein, poly r(C) binding protein 1 (PCBP1) or heterogeneous nuclear ribonucleoprotein E1 (hnRNPE1) expression correlates withmiR-3978 expression and that hnRNP E1 itself functions as a suppressor of tumor progression." (PMID 29138420, 2017). "We further investigated the relationship of PCBP1 and v6 on tumor cell invasion." (PMID 20361869, 2010). "Since PCBP1 was a negative regulator of CD44 v6 expression and tumor invasion, we further examined whether a correlation of the expression status of PCBP1 and CD44 v6 exists in primary HCCs." (PMID 20361869, 2010). "Taken together, our present study suggests a negative role of PCBP1 in CD44 variants splicing and cell invasion in HepG2 cells, which raises the possibility that down-regulation of PCBP1 might be a biomarker in tumor metastasis." (PMID 20361869, 2010). "Although the functions of PCBPs in alternative mRNA splicing, translation silencing and transcriptional regulation have been widely reported, only a few studies suggest that PCBP1 might play a role in tumor invasion." (PMID 20361869, 2010). "In addition to a number of reported mRNA transcripts, such as ILEI, EGFR, MOESIN, FAM3C, JAK2 and EIF5A2, we identified ZEB2, an EMT‐related transcription factor that is vital for tumor metastasis, as a potential transcript regulated by PCBP1 at the translational level." (PMID 41117067, 2025). "Notably, PCBP1 has been shown to impede autophagic flux in tumor cells." (PMID 40274762, 2025). "In addition to participating in tumour metastasis, PCBP1 has other important functions." (PMID 35907982, 2022). "Consequently, genetic disruption of PCBP1 in T cells exacerbates tumor growth." (PMID 32245497, 2020). "Therefore, PCBP1 could be a novel marker for cancer diagnosis and therapy, and the tumor cell cycle inhibition strategy would be of help to the therapy of PCBP1-depleted tumors." (PMID 30086790, 2018). "Thus, investigation of the alternative PCBP1 function in tumorigenesis would unravel other unknown events which would be of help to tumor diagnosis and therapy." (PMID 30086790, 2018). "PCBP1 could inhibit the v6 expression induced by Ras activation and HGF and then break the positive feedback loop, suggesting that PCBP1 might function as a candidate tumor suppressor and play a potential role in the gene therapy of malignant tumors with v6 overexpression." (PMID 20361869, 2010). "Therefore, it is tempting to speculate that the activity of PCBP1 could influence tumor cell invasion by regulating the CD44 v6 expression." (PMID 20361869, 2010). "GPX4, PCBP1, and PCBP2 protein levels were reduced in tumor tissues in a dose-dependent manner, which was consistent with the results of the in vitro experiments." (PMID 40619432, 2025). "In this study, big data analysis revealed that PCBP1, ACSL4, and ALOX15 were differentially expressed in both tumor and normal tissues of NSCLC." (PMID 39845670, 2024).
tumor (continued). "The weights of the tumours excised from BALB/c nu mice were measured, and PCBP1 suppressed tumour growth and weight." (PMID 35907982, 2022). "To elucidate the role of hnRNP E1 in the primary tumor axonogenesis, we generated a PyMT-MMTV mouse model deleted for hnRNP E1/PCBP1 expression." (PMID 34810279, 2022). "We validated five regulated alternative splicing events affected by PCBP1 using RT-qPCR and found that there was a significant difference in the expression of APOC1 and SPHK1 between tumour and normal tissues." (PMID 34857818, 2021). "After knocking down endogenous PCBP1, both HepG2 cells and SMMC7721 cells showed enhanced invasion ability, suggesting that PCBP1 inhibited tumour invasion and metastasis." (PMID 34857818, 2021). "Similarly, p62 expression is evidently reduced in tumors, compared with the normal tissues, but no clear alteration among tumors, regarding tumor stages and metastatic states, indicating that PCBP1-p62 signaling axis may play repressive role only in the tumor initiation stage." (PMID 32922440, 2020). "Furthermore, expression of four proteins is associated with tumor progression/high risk AML: DOT1L, mTOR, VIM and ZNF521, whereas the expression of six proteins is associated with tumor suppression/low risk AML: AEBP2, CAST, CBFB, LSP1, MAP1S and probably PCBP1." (PMID 30634713, 2019). "Our previous study revealed that PCBP1 translationally represses metastatic PRL-3 and its overexpression inhibits tumorigenesis, whereas PCBP1 knockdown in turn enhances tumor formation." (PMID 30086790, 2018). "Furthermore, we also searched The Human Protein Atlas database and found a set of renal tumors, in which patients with low PCBP1 level more likely show the higher tumor stage and poor five-year survival rate, indicating that PCBP1 could be a novel predictor of prognosis in cancer patients." (PMID 30086790, 2018). "Furthermore, as the first identified small molecule inhibitors of PCBP1 and PCBP2, we evaluated the efficacy and safety of ACE-induced ferroptosis in tumor therapy." (PMID 40619432, 2025). "In our study, we found that PCBP1 was decreased in LUAD tumour tissues compared to matched normal tissues." (PMID 35907982, 2022). "Altogether, these data suggest that PCBP1 mediates lung metastasis and LUAD tumour growth." (PMID 35907982, 2022). "PCBP1 is involved in regulating the stability of intracellular iron, and our study found that PCBP1 regulates ferroptosis in tumour cells (data not shown)." (PMID 35907982, 2022). "We have uncovered that PCBP1 delays the translation of metastatic PRL-3 which is broadly downregulated in variety of tumors, indicating that PCBP1 could be a potential tumor suppressor." (PMID 32922440, 2020). "PCBP1 can suppress tumorigenesis, but we still also do not understand if it is related to tumor cell death." (PMID 32922440, 2020). "Meanwhile, PCBP1 upregulates p62/SQSTM1 via inhibition p62/SQSTM1 autophagolysome and proteasome degradation as well as its mRNA stability, consequently accompanying with the caspase 3 or 8 activation for tumor cell apoptosis." (PMID 32922440, 2020). "Ectopic expression of PCBP1 inhibits tumor invasion and knockdown of endogenous PCBP1 expression stimulates invasion, suggesting a negative role of PCBP1 in tumor metastasis." (PMID 20361869, 2010). "Invasion assay suggested that PCBP1 played a negative role in tumor invasion and re-expression of v6 partly reversed the inhibition effect by PCBP1." (PMID 20361869, 2010). "Furthermore, we also observed that p62 is consistently higher in PCBP1 positive-adjacent tissue, while consistently lower in pT1 (without pelvic spread) and pT3 tumor tissue with downtrend." (PMID 32922440, 2020). "Our previous results showed that the frequency of the examined tumor samples with PCBP1 downregulation is much more than that with PRL-3 upregulation, implying that PCBP1 could play multiple tumor suppressive roles, instead of just slowing PRL-3 protein translation." (PMID 30086790, 2018).
tumor (continued). "Immunoprecipitation with anti-PCBP1 antibody, but not a control mouse IgG, showed significant enrichment of miR-3978 and miR-6124, but not miR-3148 or miR-390 in normal tissue compared to tumor tissue." (PMID 29138420, 2017). "Supporting this hypothesis, Wang and collaborators showed that overexpression of PCBP1 changes splice site usage at STAT3 exon 23 by binding to an exonic splicing suppressor site, promoting the switch from the oncogenic longer STAT3α isoform to the shorter tumor-suppressive STAT3β isoform." (PMID 37537282, 2023).